UBD (ubiquitin like modifier D)
Description:
Ubiquitin-like protein modifier which can be covalently attached to target proteins and subsequently leads to their degradation by the 26S proteasome, in a NUB1-dependent manner. Conjugation to the target protein is activated by UBA6 via adenylation of its C-terminal glycine. Promotes the expression of the proteasome subunit beta type-9 (PSMB9/LMP2). Regulates TNF-induced and LPS-mediated activation of the central mediator of innate immunity NF-kappa-B by promoting TNF-mediated proteasomal degradation of ubiquitinated-I-kappa-B-alpha. Required for TNF-induced p65 nuclear translocation in renal tubular epithelial cells (RTECs). May be involved in dendritic cell (DC) maturation, the process by which immature dendritic cells differentiate into fully competent antigen-presenting cells that initiate T-cell responses. Mediates mitotic non-disjunction and chromosome instability, in long-term in vitro culture and cancers, by abbreviating mitotic phase and impairing the kinetochore localization of MAD2L1 during the prometaphase stage of the cell cycle. May be involved in the formation of aggresomes when proteasome is saturated or impaired. Mediates apoptosis in a caspase-dependent manner, especially in renal epithelium and tubular cells during renal diseases such as polycystic kidney disease and Human immunodeficiency virus (HIV)-associated nephropathy (HIVAN).
Synonyms: FAT10; UBD-3
Tractability: Small molecule: a structure with a bound ligand is known.
Gene: Protein-coding gene on chromosome 6 (29,555,515 to 29,559,732, reverse strand). Ensembl gene ENSG00000213886.
Subcellular location: Nucleus; Cytoplasm
Subcellular location (Human Protein Atlas): Nucleoplasm; Nucleoli fibrillar center
Pathways (Reactome):
Metabolism of proteins: Neddylation
Gene Ontology:
Molecular function: proteasome binding; protein binding
Biological process: aggresome assembly; myeloid dendritic cell differentiation; positive regulation of apoptotic process; positive regulation of canonical NF-kappaB signal transduction; protein ubiquitination; regulation of mitotic cell cycle phase transition; response to tumor necrosis factor; response to type II interferon; ubiquitin-dependent protein catabolic process; protein modification by small protein conjugation; proteolysis; response to stress
Cellular component: aggresome; nucleoplasm; nucleus; cytoplasm; cytosol
Genetic constraint (gnomAD): Loss-of-function variants: 1 observed, 2.96 expected, observed/expected ratio (o/e) 0.34, 90% interval 0.12 to 1.48. That is too few expected variants to judge how well the gene tolerates losing a copy. Missense variants: 175 observed, 209.71 expected, observed/expected ratio (o/e) 0.83, 90% interval 0.74 to 0.95. Synonymous variants: 75 observed, 80.18 expected, observed/expected ratio (o/e) 0.94, 90% interval 0.77 to 1.13.
Homologues: Orthologues: chimpanzee UBD (96% identical), macaque UBD (91% identical), pig UBD (73% identical), rabbit UBD (72% identical), rat AC112568.1 (71% identical), mouse Ubd (69% identical). Paralogues in human: RPS27A (23% identical), UBC (22% identical), UBA52 (20% identical), ANKUB1 (16% identical), UBL4A (16% identical), ISG15 (15% identical), ZFAND4 (15% identical), UBL4B (13% identical), NEDD8 (13% identical), UBB (5% identical).
Diseases named in the same sentence as UBD in open-access papers:
UBD is named in the same sentence as 112 diseases in open-access papers, as found by Europe PMC text mining. Sharing a sentence is not in itself a finding about the gene and the disease. The quoted sentences say what the papers report.
hepatocellular carcinoma (21 papers, 2009 to 2026). A malignant tumor that arises from hepatocytes. "UBD interacts with WNT1-inducible signaling pathway protein 1 (WISP1), thus inducing its degradation in hepatocellular carcinoma (HCC)." (PMID 34350116, 2021). "UBD/FAT10, which we found to be hypomethylated in high BMI BE patients, is of interest as this gene has been shown to be overexpressed in hepatocellular carcinoma (HCC) and is thought to modulate the β-catenin/TCF4 pathway and drive HCC invasion and metastasis." (PMID 27795744, 2016).
colon cancer (10 papers, 2010 to 2023). "In patients with stage IIB–IIC colon cancer, the expression of UBD has been identified as a recurrent risk and associated with STS after surgery." (PMID 34411146, 2021). "This is the first report showing the association of upregulated human colon cancer UBD expression with cancer progression and recurrence independent of Pathological Tumour-Node-Metastasis staging." (PMID 20808312, 2010). "UBD was overexpressed in tumour tissue and was associated with aggressive colon cancer phenotypes." (PMID 20808312, 2010). "UBD which also contributes to colon cancer progression was observed to be upregulated in the datasets and its expression was predicted to be induced by TNF-α in transformed epithelial cells." (PMID 34946170, 2021). "It is worth noting that strong UBD staining was observed in metastatic colon cancer cells within positive lymph nodes." (PMID 20808312, 2010). "Positive UBD protein expression was signicantly higher in metastatic colon cancer cells within lymph nodes than in matched primary tumours." (PMID 20808312, 2010). "Further experimentation is required to define the molecular mechanisms governing the potential role UBD expression in colon cancer progression." (PMID 20808312, 2010). "In contrast, UBD expression was obvious in the majority of colon tumour specimens, with weak staining in 71 (35%) cases, strong staining in 64 (31%) cases and negative staining in 68 (33%) cases." (PMID 20808312, 2010). "In the 66 matched specimens available for analysis, the rate of positive UBD expression in colon cancer lymph node metastatic cells was higher than in the paired primary tumours (55/66, 83% vs 46/66, 69% P=0.002)." (PMID 20808312, 2010). "Our recent study observed that the expression of ubiquitin D (UBD), a member of ubiquitin-like modifier family, was upregulated in colon cancer parenchymal cells." (PMID 20808312, 2010). "Further validation by immunohistochemistry showed that 66% (135/203) of primary colon cancers had positive UBD protein staining, whereas only 6% (12/203) of normal colonic epithelium were immunoreactive for UBD." (PMID 20808312, 2010). "In the present study, we first measured UBD expression in fresh frozen specimens of colon cancer and found that UBD mRNA and protein expression levels were higher in colon tumour tissue than in the surrounding noncancerous mucosa." (PMID 20808312, 2010). "UBD has been reported to be overexpressed in colon cancer and may contribute to the progression of colon carcinogenesis, as well as function as a prognostic indicator." (PMID 28177879, 2017). "These strong correlations suggest that UBD overexpression might promote tumour invasion and metastasis, and that UBD could possibly be used a biomarker for identification of subsets of colon cancer with a more aggressive phenotype." (PMID 20808312, 2010). "In addition, colon cancer patients with high UBD expression have a higher recurrence rate and worse prognosis after 5-FU chemotherapy on the basis of surgery than those with low UBD expression." (PMID 34350116, 2021). "However, there are currently no published reports on the possible association of UBD expression with the clinicopathological features of colon cancer." (PMID 20808312, 2010). "The clinical significance and prognostic value of UBD expression in colon cancer has not been reported." (PMID 20808312, 2010). "Of the 30 randomly selected, paired cases used for evaluating UBD mRNA and protein expression, 22 (73%) colon cancers showed at least a two-fold increase in UBD mRNA level as compared with that of the adjacent, non-cancerous tissue." (PMID 20808312, 2010). "Overexpression of UBD in stage II and III colon cancer may correlate with disease recurrence." (PMID 20808312, 2010).
viral infection (10 papers, 2012 to 2025). "Intriguingly, the authors also showed that the NASH patient-derived cells express high levels of Ubiquitin D (UBD), an inhibitor of RNA virus-induced interferon signaling, and hypothesized that they are more susceptible to virus infection." (PMID 36233151, 2022).
breast carcinoma (9 papers, 2011 to 2026). "Elevated UBD expression was significantly associated with improved OS in breast cancer (BRCA; p=0.009, HR = 0.949) and exerted a protective effect in melanoma (SKCM; p<0.001, HR = 0.891) and sarcoma (SARC; p=0.006, HR = 0.899)." (PMID 41347086, 2025). "In the present investigation, we established that UBD expression is considerably enhanced in breast cancer, with a pronounced increase observed specifically in invasive TNBC." (PMID 41583390, 2026). "The high levels of SUMO2, ISG15, NEDD8, and UBD are related to worse prognosis outcomes in breast cancer." (PMID 41583390, 2026). "To corroborate these results, we conducted an examination of the GSE42568 dataset, which confirmed that UBD levels were significantly higher in breast cancer tissues." (PMID 41583390, 2026). "The study offers initial proof that SPIB directly binds to the UBD promoter to influence its transcription in breast cancer, promoting TNBC cell proliferation and migration by increasing UBD levels." (PMID 41583390, 2026). "UBD was reported to enhances breast cancer metastasis by stabilizing ZEB2 and facilitating the EMT process." (PMID 41583390, 2026). "Nonetheless, the molecular mechanisms responsible for UBD up-regulation in breast cancer are not well understood." (PMID 41583390, 2026). "Previous study has indicated that UBD (FAT10/Ubiquitin D) promotes the invasion of the progressive breast cancer cell by stabilizing ZEB2." (PMID 37475016, 2023). "For instance, UBD shows elevated expression levels in breast cancer, and its down-regulation has been found to inhibit epithelial–mesenchymal transition (EMT) and the metastatic behavior of breast cancer cells, possibly through the stabilization of the ZEB2 protein." (PMID 41583390, 2026). "This indicates that UBD may play a pivotal oncogenic role in the advancement of breast cancer and could represent a viable prognostic and therapeutic target." (PMID 41583390, 2026). "Subsequently, immunohistochemical (IHC) analyses were performed on 80 breast cancer specimens alongside adjacent normal tissues, demonstrating that UBD was expressed at significantly higher levels in invasive tumor tissues as opposed to adjacent normal tissues and ductal carcinoma in situ." (PMID 41583390, 2026). "Increased UBD expression was also found in breast cancer tissues." (PMID 35812403, 2022). "An evaluation of UBD expression across different metastatic sites revealed notably increased levels in lung metastases of breast cancer as opposed to other distant metastases." (PMID 41583390, 2026). "These suggested that HECTD3, PSMB10, UBD, UBE2C, and UBE2S might also affect the efficacy of neoadjuvant chemotherapy in breast cancer through the ubiquitin proteasome pathway." (PMID 29685151, 2018). "Besides, HECTD3, PSMB10, UBD, UBE2C, and UBE2S involved in the ubiquitin proteasome pathway, as well as CCL2, CCR1, CXCL10, CXCL11, and IL2RG implicated in the cytokine–cytokine receptor interaction pathway, might be used for evaluating the efficacy of neoadjuvant chemotherapy in breast cancer." (PMID 29685151, 2018).
bladder cancer (8 papers, 2016 to 2025). "Conversely, UBD expression exerted a protective effect in bladder cancer (BLCA; p=0.012, HR = 0.927) and SKCM (p<0.001, HR = 0.884)." (PMID 41347086, 2025).
colorectal cancer (5 papers, 2021 to 2025). A primary or metastatic malignant neoplasm that affects the colon or rectum. "We found that knocking down UBD significantly inhibited the viability and capacity of colorectal cancer cells to grow in vitro, arresting the cells in G1 phase." (PMID 34350116, 2021). "Ubiquitin D (UBD) is a member of the ubiquitin-like modifier (UBL) family and is highly expressed in a variety of cancers including colorectal cancer (CRC)." (PMID 34350116, 2021).
liver cancer (5 papers, 2018 to 2025). An epithelial or non-epithelial malignant neoplasm that arises from the liver. "Although the role of UBD has been investigated in other cancers, such as breast and liver cancer, its specific mechanisms in OC remain poorly understood." (PMID 40692714, 2025).
diabetes (4 papers, 2018 to 2022). "SULT1C2 and UBD (ubiquitin D) were responsible for progression of kidney diseases, but these genes might be liable for advancement of obesity associated type 2 diabetes mellitus." (PMID 33902539, 2021). "From these and previously reported results, it is likely that the genes encoding UBD, UBASH3A and TCRVβ13a participate in pathways that initiate and lead to diabetes." (PMID 34205929, 2021). "The results of Western blot validation showed that dynamic changes in proteins, such as IGF2, Ly6a, Grb10, and UBD, occurred to regulate the incidence of diabetes by influencing the insulin receptor substrate (IRS) signaling pathway." (PMID 30131712, 2018). "The hub genes CEBPD, TP73, ESR2, TAB1, MAP 3K5, FN1, UBD, RUNX1, PIK3R2 and TNF, which might play an essential role in obesity associated type 2 diabetes mellitus was further screened." (PMID 33902539, 2021). "Ubiquitin D (UBD) expression is upregulated in the pathogenesis of diabetes, and UBD inhibits the activity of insulin receptor substrates 1 and 2 (IRS1 and IRS2), diminishing their ability to accept insulin, which leads to the downregulation of PI3KR1 expression and causes insulin resistance." (PMID 30131712, 2018).
liver fibrosis (4 papers, 2019 to 2026). "Notably, UbD deficiency (in UbD−/− mice) suppressed HGF/MET signaling and MDB formation, leading to reduced liver fibrosis." (PMID 42270593, 2026).
melanoma (4 papers, 2021 to 2025). A malignant, usually aggressive tumor composed of atypical, neoplastic melanocytes. "Another noteworthy miRNA is hsa‐miR‐24; its overexpression promotes autophagy and apoptosis in melanoma cells by targeting UBD and activating JNK signalling." (PMID 39823244, 2025).
ovarian carcinoma (4 papers, 2021 to 2025). A malignant neoplasm originating from the surface ovarian epithelium. "In addition, Although Wang’s study built a five-gene risk model behaving well in prognostic prediction, the role of some genes, such as UBD, ATP1A3, and HLA-DOB, remains unclear in ovarian cancer." (PMID 37095524, 2023).
gastric cancer (3 papers, 2010 to 2021). A primary or metastatic malignant neoplasm involving the stomach. "Overexpression of UBD in gastric cancer has been correlated with metastasis and tumour staging, and both UBD mRNA and protein levels were identified as independent prognostic factors for this disease." (PMID 20808312, 2010). "UBD was reported to be localized in the nuclei of hepatocellular and gastric cancer cells, indicating that it might mediate transcriptional control and tumour development." (PMID 20808312, 2010).
Insulin resistance (3 papers, 2018 to 2024). Increased resistance towards insulin, that is, diminished effectiveness of insulin in reducing blood glucose levels. "By our validation experiment, either overexpression or knockdown, we clarified the direct negative correlation between UBD expression and p-akt level, a major insulin resistance index." (PMID 38595789, 2024).
lymphoma (2 papers, 2013 to 2022). A malignant (clonal) proliferation of B- lymphocytes or T- lymphocytes which involves the lymph nodes, bone marrow and/or extranodal sites. "Based on the gene expression studies, we identified BAT3/BAG6, HIGD1A, and FAT10/UBD as immunohistochemical markers expressed in the tumor cells of all three lymphomas." (PMID 24244368, 2013).
Obesity (2 papers, 2021 to 2023). Accumulation of substantial excess body fat. "In total, we identified a total of 3,298 differentially expressed genes, among which we discovered key genes such as UBD, RGS2, FASN, and SCD that have functions related to adipogenesis, body weight, obesity, and lipid metabolism." (PMID 38264212, 2023).
psoriasis (2 papers, 2020 to 2023). An autoimmune condition characterized by red, well-delineated plaques with silvery scales that are usually on the extensor surfaces and scalp. "Our GNN also succeeds in separating 83 healthy skin samples from 95 lesional psoriasis samples, revealing that upregulation of 26S- and NUB1-mediated degradation of NEDD8, UBD, and their conjugates is central to the largest perturbed reaction network component in psoriasis." (PMID 37521042, 2023).
Skin Cutaneous Melanoma (2 papers, 2021 to 2022). "Silenced expression of UBD, regulated by miR-24-1-5p could enhance autophagy and apoptosis of human skin melanoma cells." (PMID 34411146, 2021).
steatosis (2 papers, 2018 to 2020). Increased lipid within the cytoplasm of cells. "Six progress-related genes (AKR1B10/SPP1/CD24/UBD/FABP4/STMN2) were found remarkably correlated with steatosis, ballooning, inflammation, fibrosis, and NAS in the progress of Normal/NAFL/NASH." (PMID 33574818, 2020).
thyroid cancer (2 papers, 2023 to 2025). "UBD was upregulated in 14 cancers but downregulated in thyroid carcinoma (THCA) and kidney chromophobe (KICH)." (PMID 41347086, 2025). "Our analysis revealed that UBD was significantly upregulated in 14 cancer types and downregulated in two malignancies (KICH: Kidney Chromophobe; THCA: Thyroid Carcinoma)." (PMID 41347086, 2025).
anemia (1 paper, 2024). A reduction in the number of red blood cells, the amount of hemoglobin, and/or the volume of packed red blood cells. "These mice exhibited anemia, thrombocytopenia, abnormally small megakaryocytes, extramedullary hematopoiesis, and BMF, indicating that the polyubiquitin‐binding function of ABIN1 through its UBD is crucial for normal hematopoietic development." (PMID 38009796, 2024).
breast tumors (1 paper, 2011). "Like MKI67, which encodes the proliferation-related antigen Ki-67, the expression of most of these genes (except CCNB3 and UBD) increased during the transition from grade I to ductal grade III breast tumors." (PMID 21352579, 2011).
cervical squamous cell carcinoma (1 paper, 2021). A squamous cell carcinoma arising from the cervical epithelium. "UBD was also overexpressed in cervical squamous cell carcinoma tissues and associated with tumor size and lymphatic metastasis." (PMID 34411146, 2021).